EZR (ezrin)
Diseases named in the same sentence as EZR in open-access papers (continued):
Sharing a sentence is not in itself a finding about the gene and the disease.
asthma (5 papers, 2008 to 2022). "Some newly detected EV-related proteins were linked to asthma pathology: ezrin, contantin-1 (CNTN1) and Plexin B2 (PLXNB2)." (PMID 36466836, 2022). "Recent studies have shown that ezrin, whose function is affected by extensive phosphorylation and protein interactions, is closely associated with asthma, may be a therapeutic target for asthma treatment." (PMID 36530558, 2022). "Despite this relatively good control, ezrin negatively correlated with FEV1 in our study, supporting the notion that serum ezrin levels, to some extent, reflect asthma severity." (PMID 35807067, 2022). "In this review, we summarize studies on the structure, distribution, and regulation of ezrin, and discuss its role in airway inflammation and remodeling in asthma." (PMID 36530558, 2022). "In contrast to our results, a recent study found that the ezrin levels measured in serum were lower in asthma patients compared with non-asthma controls." (PMID 35807067, 2022). "In this review, we summarize studies on ezrin and discuss its role in asthma-related airway inflammation and remodeling." (PMID 36530558, 2022). "EV-associated ezrin released by AECs contributed to IL-13-induced epithelial damage via the TNF-α-dependent pathway and was proposed as a biomarker of asthma control." (PMID 36466836, 2022). "Results have shown that ezrin can contribute to asthma by affecting bronchial epithelium repair via RhoA pathways." (PMID 34065716, 2021). "Research demonstrates that ezrin may have a role in the pathogenesis of asthma by affecting both bronchial epithelial repair and contraction of airway smooth muscle cells." (PMID 36530558, 2022). "Increasing attention has been paid to ezrin in asthma pathophysiology." (PMID 36530558, 2022). "The role of ezrin in the pathogenesis of asthma is, as yet, poorly understood." (PMID 35807067, 2022). "In addition, serum ezrin levels were found to be related to the level of asthma control, the worse the control, the lower the ezrin levels." (PMID 35807067, 2022). "Ezrin may be a potential biomarker of epithelial damage in asthma." (PMID 36530558, 2022). "We summarized that ezrin regulates airway inflammation through type 2 immune cells, mast cells, neutrophils, and B cells and participates in airway remodeling via epithelial cells, EMT, ASM cells, and fibroblasts in asthma." (PMID 36530558, 2022).
endometriosis (5 papers, 2020 to 2025). The growth of functional endometrial tissue in anatomic sites outside the uterine body. "At this point, it is still unclear if Ezrin and Phospho-Ezrin are a cause or consequence of endometriosis." (PMID 35793608, 2022). "It is still unclear if Ezrin and Phospho-Ezrin are a cause or consequence of endometriosis." (PMID 35793608, 2022). "The expression of miR-183 and Ezrin was negatively correlated in ectopic endometrium tissues of endometriosis patients." (PMID 40630207, 2025). "The present study investigated the expression and role of miR-183 in the proliferation, invasion, migration, and apoptosis of endometrial stromal cells in endometriosis patients and the potential involvement of targeting Ezrin." (PMID 40630207, 2025). "In an immunohistochemistry study, the authors found that a-actinin and talin cytosynthetic proteins are dysregulated in endometriosis and EC, while ezrin is only in EC." (PMID 38731868, 2024). "It was observed that the levels of ezrin and Rho pathway were higher in ectopic endometrium, which is consistent with the clinical stages of endometriosis." (PMID 36968198, 2023). "The study on endometriosis suggested that Ezrin T567 phosphorylation has been involved in the remodeling of the cytoskeleton of ectopic endometrial stromal cells (ESCs)." (PMID 36968198, 2023). "Elevated expression of ezrin was observed in ectopic endometrium, which is consistent with the clinical stages of endometriosis." (PMID 36968198, 2023). "Recent studies have shown that the expression and localization of ezrin have been altered in tissues related to endometriosis, recurrent miscarriage, gestational trophoblastic disease, and polycystic ovary syndrome (PCOS), sparking our interest." (PMID 36968198, 2023). "All the three groups with different immunostaining intensities for Ezrin were similar in age, BMI, menstrual cycle phase, and endometriosis ASRM stage." (PMID 35793608, 2022). "Some studies previously evaluated the relation between Ezrin and cancer, 11, 12 and also the relationship between these proteins and endometriosis." (PMID 35793608, 2022). "In this study, the authors evaluated the possible role of Ezrin and Phospho-ezrin in different types of lesions of endometriosis." (PMID 35793608, 2022). "We further explored whether miR-183 expression influences the malignant behaviors of endometrial stromal cells in endometriosis patients by targeting Ezrin." (PMID 40630207, 2025). "miR-183 may play a suppressor role in endometriosis by downregulating Ezrin to inactivate the Rho/ROCK pathway." (PMID 40630207, 2025). "In endometriosis tissues, reduced miR-183 levels lead to increased RhoA and Ezrin expression." (PMID 40630207, 2025). "The expression status of RhoA/ROCK/Ezrin in endometriosis was verified by animal models." (PMID 40630207, 2025). "Our results show that miR-183, which is expressed in low levels in endometrial of endometriosis patients, may suppress the invasion and migration of endometrial stromal cells in endometriosis patients by targeting Ezrin via the Rho pathway." (PMID 40630207, 2025). "Moreover, activation of the Rho/ROCK signaling pathway also plays an important role in the development of endometriosis and is closely related to ezrin." (PMID 40630207, 2025). ",14, 15, 16 Like in cancer, the Ezrin protein was also evaluated in some studies related to endometriosis’ invasiveness, increasing cell migration and adhesion in ectopic endometrial cells, mainly due to its capacity in remodeling and organizing the cytoskeleton." (PMID 35793608, 2022). "Additionally, the inflammatory microenvironment of endometriosis was not addressed; future work should explore crosstalk between miR-183/Ezrin and cytokines." (PMID 40630207, 2025).
nasopharyngeal carcinoma (5 papers, 2012 to 2022). A carcinoma arising from the nasopharyngeal epithelium. "A high expression of ezrin was related to poor outcome, which supported findings in HNSCC, ESCC, NSCLC, salivary gland adenoid cystic carcinoma, nasopharyngeal cancer, and endometrioid carcinoma." (PMID 23209815, 2012). "Similarly, circARHGAP12 enhances the stability of EZR mRNA by binding to the 3’UTR of EZR mRNA, thereby promoting the progression of nasopharyngeal carcinoma (NPC)." (PMID 36465346, 2022). "In nasopharyngeal carcinoma, circARHGAP12 is significantly upregulated and regulates the expression of cytoskeletal remodeling-related proteins (EZR, TPM3, and RhoA) through directly binding the mRNA 3′-UTR and promoting its stability via EZR/TPM3/RhoA complex." (PMID 34392306, 2021). "Similarly, circARHGAP12 promotes the progression of nasopharyngeal carcinoma (NPC) by binding to 3′ UTR of EZR mRNA, which enhances the stability of EZR mRNA." (PMID 34445958, 2021).
renal carcinoma (5 papers, 2012 to 2021). A carcinoma arising from the epithelium of the renal parenchyma or the renal pelvis. "Here, we present evidence that TMIGD1 binds to ERM family proteins (moesin and ezrin), regulates the stability of microtubules and modulates cell migration in renal cancer cells, implicating TMIGD1 as a potential cancer therapeutic target." (PMID 34503512, 2021). "In renal cancer, the interaction between EZR and PODXL occurs through EBP50, which serves as a scaffolding protein." (PMID 26135398, 2015). "For example, the expression status of TMIGD1 in human cancers, such as colon and renal cancers, could determine whether moesin and ezrin function as pro- or anti-tumorigenic factors." (PMID 34503512, 2021). "In conclusion, it was found that expression of miR-96 was negatively correlated with the metastatic ability of RCC, and that downregulation of miR-96 could suppress the invasion of renal cancer cell via downregulation of Ezrin expression." (PMID 26419932, 2015). "The function of CLIC5 is proposed to be similar to that of EBP50, which is responsible for the interaction between EZR and PODXL in renal carcinoma." (PMID 26135398, 2015). "An increase of CD44 protein was observed in Caki-1 renal cancer cells following hypoxia, which was attributed to the Rho kinase-mediated activation of ERM (Ezrin, Radixin, Moesin) proteins during hypoxia, since ERM proteins are associated with the cytoplasmic domain of CD44." (PMID 22937154, 2012).
Sjögren’s syndrome (5 papers, 2021 to 2025). "Similarly, AQP5 interacts with ezrin, forming complexes that are mislocated in the salivary glands of Sjögren’s syndrome patients." (PMID 39941100, 2025). "Therefore, we assume that dysregulation of ezrin-mediated AQP5 trafficking to the plasma membrane may be related to exocrine dysfunctions in Sjögren’s syndrome." (PMID 34948308, 2021). "Similar to ezrin, prolactin-inducible protein (PIP) can interact with AQP5, controlling its localization in Sjögren’s syndrome patients’ salivary glands." (PMID 39941100, 2025). "Abnormal distributions of ezrin or AQP5 in exocrine gland tissues have been reported in some Sjögren’s syndrome patients." (PMID 34948308, 2021). "AQP5–ezrin complexes were assessed by PLA in hMSG biopsies from patients presenting sicca symptoms but without evidence of autoimmunity suggestive of Sjögren’s syndrome (SICCA-NS; used as control) and patients presenting sicca symptoms and Sjögren’s syndrome (SICCA-SS)." (PMID 34502121, 2021). "Furthermore, in salivary gland biopsies from patients with Sjögren’s syndrome, an autoimmune disease in which the destruction of exocrine glands leads to severe eye and mouth dryness, AQP5 and ezrin were both mislocalized, supporting the importance of ezrin for AQP5 trafficking." (PMID 39062914, 2024).
squamous cell carcinoma (5 papers, 2014 to 2024). A carcinoma arising from squamous epithelial cells. "A tumorigenic role of Ezrin in skin cancer has also been demonstrated using immunohistochemical staining specimens from epithelial skin tumors, together with squamous carcinoma cell lines." (PMID 33240887, 2020). "Ezrin and Rho-A expressions in squamous cell carcinoma suggest a cooperative participation of these proteins in cell movement and invasion." (PMID 33240887, 2020). "Ezrin expression was shown to be higher in squamous cell carcinoma compared with less aggressive tumors such as Bowen's disease, actinic keratosis, keratoacanthoma, and seborrheic keratosis." (PMID 25580109, 2014). "Ezrin, ERK, STAT3, and AKT appear to be involved in the progress from carcinoma in situ in the tongue into squamous cell carcinoma." (PMID 32281236, 2020).
acute kidney injury (4 papers, 2024 to 2025). Sudden and sustained deterioration of the kidney function characterized by decreased glomerular filtration rate, increased serum creatinine or oliguria. "Their work identified Ezrin K263 as the predominant lactylation site, underscoring the role of lactylation in metabolic reprogramming and inflammatory responses within renal tubular epithelial cells during sepsis-associated acute kidney injury (S-AKI)." (PMID 40860191, 2025). "In sepsis‐associated acute kidney injury, LPS stimulation has been demonstrated to increase H3K18 and Ezrin lactylation, thereby activating the RhoA‐ROCK1‐Ezrin signalling pathway." (PMID 41190507, 2025).
bladder cancer (4 papers, 2014 to 2023). "In several cancer forms, high expression of ezrin has been associated with more aggressive tumours, whereas in serous ovarian carcinoma, lost expression of ezrin correlated with a worse prognosis, similar to the findings in bladder cancer." (PMID 24885195, 2014). "For example, the expression level of Ezrin in bladder cancer is reduced while it is commonly up-regulated in many other cancer types." (PMID 33240887, 2020). "Immunohistochemical expression of ezrin was evaluated in tissue microarrays with tumours from one retrospective cohort of bladder cancer (n = 110; cohort I) and one population-based cohort (n = 342; cohort II)." (PMID 24885195, 2014). "Since the only previous study on the prognostic value if ezrin expression in bladder cancer was performed on tumours from patients with T1 tumours, the prognostic value of ezrin expression in subgroups according to T-stage was also examined." (PMID 24885195, 2014). "However, positive Ezrin expression was a predictor of good prognosis in bladder cancer for OS (HR = 0.49, 95% CI: 0.27–0.78, P = 0.004)." (PMID 26632332, 2015). "However, individuals elevating Ezrin expression had a significantly improved survival of bladder cancer (HR = 0.46, 95% CI: 0.27–0.78, P = 0.004) among Caucasians." (PMID 26632332, 2015). "In addition, it was found that TCs in normal tissues with ezrin expression may compete for invasiveness and may be an indicator that can be used to reduce the recurrence rate of bladder cancer." (PMID 37986278, 2023). "Although these reports collectively suggested the prognostic value of Ezrin in bladder cancer, its immunohistochemical expression level failed to predict therapy effect." (PMID 33240887, 2020). "In few cases such as bladder cancer, higher Ezrin expression indicates better prognosis rather than worse." (PMID 33240887, 2020).
cervical (4 papers, 2013 to 2017). "Thus, the further study is needed to verify the mechanism whether HPV mediates the progression of the EMT via Ezrin in cervical tumorigenesis." (PMID 26933912, 2016). "However, further study is needed to verify the hypothesis and to explore the mechanism by which HPV mediates the progression of the epithelial-mesenchyme transition (EMT) via ezrin in cervical tumorigenesis." (PMID 24182314, 2013). "The positive expressions of ezrin and galectin-3 in CIN group were higher than in cervicitis group (both P<0.05), but the differences of positive ezrin expression rate among CIN grade I, II and III were not statistically significant (all P>0.05)." (PMID 28355349, 2017).
diabetes (4 papers, 2011 to 2025). "However, abundance of ezrin was reduced at 4 weeks after induction of diabetes by streptozotocin in rats." (PMID 33046439, 2021). "Ezrin has been suggested to contribute in PTC to the uptake by micropinocytosis of advanced glycation end products (which results from the non-enzymatic glycation of proteins during chronic hyperglycemia and contribute to DKD) and thereby to promote diabetes-induced tubulointerstitial fibrosis." (PMID 32579601, 2020). "Four genes (TNFRSF12A, MAP1B, EZR and YWHAZ) upregulated in donors with chronic pancreatitis were also upregulated in vimentin-positive α-cells in donors without diabetes or CF." (PMID 39836539, 2025).
head and neck squamous cell carcinoma (4 papers, 2012 to 2021). A squamous cell carcinoma that arises from any of the following anatomic sites: lip and oral cavity, nasal cavity, paranasal sinuses, pharynx, larynx, and salivary glands. "In head and neck squamous cell carcinomas, ezrin was identified as a key molecule in tumor progression and metastatic behavior of neoplastic cells and it has been correlated with poor outcome, similarly to podoplanin." (PMID 25480364, 2014).
lupus (4 papers, 2017 to 2024). "The RhoA/ROCK pathway has been implicated in lupus pathology in a prior study that showed that increased phosphorylation of the ezrin, radixin, moesin (ERM) proteins interact with CD44 to promote the adhesion, migration and inflammatory response of T lymphocytes." (PMID 37790522, 2023). "Moreover, ezrin also regulates B cell-mediated autoimmunity, since conditional deletion of ezrin attenuates lupus in mice deficient for the Src kinase Lyn by reducing B cell activation, leukocyte infiltration and IgG deposition in the kidney glomeruli." (PMID 32098334, 2020). "In systemic lupus erythematosus (SLE) T cells, the binding of autoantibodies to the cluster of differentiation 3 (CD3)-TCR complex induces the phosphorylation of ezrin and actin polymerization." (PMID 28821013, 2017).
meningococcal infection (4 papers, 2018 to 2025). Infections with bacteria of the species neisseria meningitidis. "We also investigated host cell cytoskeleton rearrangements caused by meningococcal infection by monitoring the localization of ezrin, because the accumulation of ezrin beneath meningococci on HBMEC is required for bacterial internalization into host cells." (PMID 32866169, 2020). "In order to establish whether the same strategy is applicable to cysteine uptake, we analyzed changes in the host cell cytoskeleton upon meningococcal infection using indirect immunofluorescence to monitor the localization of ezrin." (PMID 30538184, 2018). "ICAM-1 and CD44 are massively recruited to bacterial adhesion sites during Neisseria meningitidis infection, together with the ERM proteins (ezrin), to regulate host inflammatory response by blocking the transendothelial migration of leukocytes." (PMID 41440381, 2025).
renal cell carcinoma (4 papers, 2015 to 2021). "Ezrin expression negatively correlated with renal cell carcinoma (RCC) metastasis, and the inhibition of Ezrin expression suppressed the invasive abilities of RCC cells." (PMID 33240887, 2020). "Having established a functional link between TMIGD1 and moesin, we asked whether expression profiles of the TMIGD1 and ERM family proteins, moesin and ezrin, correlate with survival of renal cell carcinoma (RCC) patients." (PMID 34503512, 2021).
viral infection (4 papers, 2012 to 2021). "Similar to ezrin and moesin, an increased level of radixin expression has been observed in many tumor tissues and it has also been implicated in the viral infection process for several viruses." (PMID 31018575, 2019). "The role that Ezrin plays during viral infection and transmission has been studied in human immunodeficiency virus-1 (HIV-1)." (PMID 33498183, 2021). "We did identify 294 DML sites in CD4+ T lymphocytes that were associated with AHI at host genes such as EZR, MDM2, and PIK3C2A that play a role in viral activity suggesting that HIV-1 may be modifying CD4+ T lymphocytes DNA methylation states to promote viral infection and replication." (PMID 34388205, 2021).